PTH (parathyroid hormone)
Diseases named in the same sentence as PTH in open-access papers (continued):
Sharing a sentence is not in itself a finding about the gene and the disease.
tumor (continued). "On immunohistochemical (IHC) staining, tumor cells showed patchy expression of CD56, but the tumor was negative for broad-spectrum keratins, PAX8, TTF1, thyroglobulin, calcitonin, HBME-3, CEA, PTH, GATA3, p63, SOX10, and S-100." (PMID 40277780, 2025). "PTH1R activation by parathyroid hormone (PTH) or PTH-related peptide (PTHrP), a tumor-derived counterpart, mobilized monocytic (M-) MDSCs from murine BM without increasing immunosuppressive activity." (PMID 37085481, 2023). "Studies have indicated that PTHR1, can be activated by its ligands, including parathyroid hormone (PTH) and parathyroid hormone‐related peptide (PTHrP), and can then exert tumour‐promoting effects." (PMID 33511766, 2021). "MIR517C was among those that showed the most significant difference and whose levels positively correlated with parathyroid hormone (PTH), serum calcium, and tumor weight." (PMID 34638805, 2021). "In this case, tumor cells were eosinophilic on hematoxylin and eosin (HE) staining, negative for TTF-1, thyroglobulin, and chromogranin A, and positive for PTH on immunostaining." (PMID 33978837, 2021). "In addition to its well characterized role in maintaining calcium homeostasis and regulating parathyroid hormone release, evidence has accumulated linking the CaSR with cellular differentiation and migration, brain development, stem cell engraftment, wound healing, and tumor growth and metastasis." (PMID 27303307, 2016). "Increased tumor-induced osteoblast activity further increases RANKL and decreases Ca2+, leading to parathyroid hormone (PTH) release, promoting osteoclast activity." (PMID 27618899, 2016). "Tumor cells produce osteoclast activating factors, such as interleukin (IL)-6, TNF-α, or ParaThyroid Hormone-related Peptide (PTH-rP), which induce osteoclast differentiation and activation." (PMID 26779435, 2015). "In one case, the tumor lacked PTH expression by immunohistochemistry, yet low levels of PTH mRNA expression were consistently detected." (PMID 40762649, 2025). "A positive correlation between tumor size and PTH was observed in the reference group (P = 0.0006) but not in the APT groups, likely due to small sample sizes." (PMID 40434298, 2025). "In view of the unremarkable parathyroid ultrasonography and normal phosphatemia, these results explicitly ruled out both PHPT and tumor-mediated ectopic PTH secretion." (PMID 41561737, 2025). "Immunohistochemically, the tumor was positive for PTH, negative for thyroid transcription factor 1 (TTF-1) and thyroglobulin, and had a Ki-67 labeling index of less than 1%." (PMID 41216108, 2025). "Several hormonal factors, like ectopic secretion of parathyroid hormone by tumours and prostaglandins activating osteoclasts, along with non-hormonal hypercalcemic factors, contribute to malignant hypercalcemia." (PMID 39559636, 2024). "In the presented case, there was no doubt about the malignant nature of the tumor; however, the positive expression of PTH and the absence of TTF-1, thyroglobulin, CK7, and HBME-1 expression made it possible to clarify its origin." (PMID 37183888, 2023). "Brown tumours have long been regarded as a purely reactive lesion, the noxious agent being the systemically elevated parathyroid hormone." (PMID 37509363, 2023). "In our patient, after confirming the presence of only one tumor in the upper mediastinum on preoperative radiological examination, the intact PTH levels were not monitored." (PMID 37341946, 2023). "Comparing with the previous 10 years from 2000-2009, the biochemical features in PHPT patients, such as serum PTH, albumin-corrected Ca, ALP concentrations all became lower; and tumor size to be smaller; kidney function and BMDs turned to be better in recent 10 years from 2010-2019." (PMID 35784571, 2022). "In addition, TgAb, TPOAb, TSH, Tg, and PTH were also tested, and US and Rx-WBS were additionally performed to monitor tumor recurrence." (PMID 36510208, 2022).
tumor (continued). "The mechanisms mediating the bone- and neoplasm-forming effects of PTH remain incompleted understood, few studies on the role of Insulin-like growth factor-binding protein 7 (IGFBP7) in mediating the anabolic effects of PTH has been reported." (PMID 35462909, 2022). "Fourth, although IGFBP7 has been implicated as a tumor suppressor, we did not evaluate the function of IGFBP7 in reducing the carcinogenic effects of PTH, and further studies are needed to address these limitations." (PMID 35462909, 2022). "It was reported that in PHPT, serum calcium level is more closely related with cell number, tumor volume and serum PTH concentration, while age and sex are not contributing factors." (PMID 35784571, 2022). "Previous studies of SERMs in pHPT have mainly focused on the pharmacological effects on bone metabolism, serum calcium and PTH secretion, without addressing the potential tumor-suppressive effects of estrogens, which are certainly of equal importance." (PMID 32331456, 2020). "Further investigation evaluating parathyroid hormone and calcitonin levels or changes to the RANK/RANK-L pathway will be required to fully understand how nabilone, via CB1/CB2 receptors protects the bone from the tumor burden." (PMID 31882872, 2019). "PGE2 secretion was high only in tumor thyroid cell lines with M2-like polarizing ability and in senescent thyrocytes; on the contrary, the non-polarizing tumor cell lines, as well as PTh and Nthy, produced low levels of PGE2." (PMID 31113465, 2019). "Bone volume and structure was unaffected by PTH throughout our study; hence, the effects on tumour growth were not due to gross alterations of the microenvironment." (PMID 30261597, 2018). "Although we did not monitor HSCs, simulation of this process is unlikely to have influenced our results, as we did not inject tumour cells until after the PTH treatment was completed." (PMID 30261597, 2018). "We observed a significant association between presence of inflammatory infiltrates and increase in the patients’ serum levels of PTH, without a significant increase in tumor weight or evidence of degenerated tumor tissue." (PMID 28855268, 2017). "PCA is a very rare disease with a delayed diagnosis especially when the patient has non-specific symptoms, the tumor is non-palpable and the serum calcium and parathyroid hormone are not too high." (PMID 29354025, 2017). "According to the immunostaining results, the tumor cells were slightly positive for PTH and chromogranin A and negative for TTF-1, thyroglobulin, calcitonin, CD5, and S100 proteins." (PMID 28726134, 2017). "If the intensity of tumor PTHimmunoreactivity is a reflection of the rightward shift in the calcium–PTH set point, ourdata indicate that it is the sheer tumor mass, rather than the pathological regulation of PTH,that determines the severity of the disease." (PMID 26865585, 2016). "Whilean interesting trend was observed, tumor PTH immunoreactivity (+1 to +4) was not significantlyassociated with serum circulating 25-hydroxyvitamin D levels (Kruskal–Wallis:P = 0.054)." (PMID 26865585, 2016). "Indeed, our semi-quantitative immunohistochemistry maybe too crude to accurately quantify the tumor PTH levels for weaker statistical relationships.While the value of vitamin D supplementation in pHPT is currently debated, it has been reportedto lower serum PTH levels." (PMID 26865585, 2016). "The clinical features are mostly due to the effects of the excessive secretion of PTH by the functioning tumor rather than to the spread of tumor mass." (PMID 26350418, 2015). "In our case, a positive staining for PTH and chromogranin A, and negative staining for thyroglobulin, confirmed the parathyroid nature of the tumor." (PMID 26350418, 2015). "Immunohistochemical studies revealed that tumor cells were strongly immunoreactive for PTH and negative for calcitonin, TTF-1, and thyroglobulin, thus confirming that the tumor cells were parathyroid in origin." (PMID 23936709, 2013).
tumor (continued). "Serum concentrations of immunoreactive PTH were not significantly altered by either tumour growth or indomethacin." (PMID 7426347, 1980). "The non-linear negative relationships between phosphate, PTH and ionized calcium may suggest heterogeneous insensitivity of tumor parathyroid cells to extracellular phosphate." (PMID 41752149, 2026). "A second, distinct mechanism involves dysregulated production of 1,25-dihydroxyvitamin D. Tumor cells and tumor-associated macrophages may aberrantly express 25-hydroxyvitamin D3-1α-hydroxylase (CYP27B1), which is not suppressed by PTH or serum calcium." (PMID 41287694, 2025). "Tumor cells were positive for PTH and APC but negative for galectin-3 and PGP9.5." (PMID 38363524, 2024). "Interestingly, PTH transcript abundance is equivalent between normal tissue, Def-Ts, and Rep-Ts, indicating that aberrant tumor-specific PTH gene expression is not a driver of hormonal hypersecretion in PHPT." (PMID 36992820, 2023). "However, PTH treatment significantly reduced the incidence of bone metastasis in mice bearing Cont-4T1 tumor but not in mice bearing Pth1rKD-4T1 tumors (4/20 vs 11/20)." (PMID 36692956, 2023). "Regardless, the preclinical data strongly suggest that any impact of PTH or PTHrP analogs on tumor progression, whether positive or negative, is likely to be mediated entirely through its paracrine effects on the bone microenvironment." (PMID 37345007, 2023). "Because such a large tumor can contain different clones of cells, a negative biopsy does not rule out that PTH could be produced from a part of the tumor not represented in the biopsy." (PMID 33413267, 2021). "Immunohistochemically, tumor cells were negative for thyroid transcription factor-1, negative for thyroglobulin, negative for chromogranin A (positive for normal parathyroid tissue within the nodule), positive for PTH, and positive for parafibromin." (PMID 33978837, 2021). "Some authors have suggested that it may be possible to determine whether a tumor is of parathyroid origin or not by measuring intact-PTH of the lavage fluid from fine needle aspiration of the lesion." (PMID 32246214, 2020). "After PC resection intra-operative PTH levels can fall significantly, although often not as quickly as with benign disease; no PTH may indicate incomplete tumour resection, or concomitant multiple gland hyperplasia, or even multiple PCs." (PMID 31142320, 2019). "In addition, PTH did not appear to make space available for tumour cells in the HSC niche, as there was no increase in the number of tumour cells homing to the long bones in PTH treated animals, compared to control." (PMID 30261597, 2018). "The mechanism underlying this differential effect of PTH between sites was not identified, as the study design did not establish whether PTH affected the primary tumour, metastatic spread, or the bone microenvironment." (PMID 30261597, 2018). "Crucially, as PTH is cleared within 2–3 h, and animals did not receive further PTH treatment after tumour cell injection, this design allowed us to assess the effects of PTH on the microenvironment, but not on the tumour cells themselves." (PMID 30261597, 2018). "Unfortunately, we could not determine the PTH-rp levels of our patient, and no tumor specimen was available for PTH-rp studies." (PMID 28977163, 2017). "PTH mRNA expression was observed, and finally we diagnosed this tumor as non-functioning PTC." (PMID 28726134, 2017). "We diagnosed this tumor as non-functioning PTC using RT-PCR for PTH mRNA." (PMID 28726134, 2017). "Interestingly, tumor CASR protein levels have previously been coupled to thedegree of shift in the calcium–PTH set point, but not to tumor size." (PMID 26865585, 2016). "Unlike parathyroid hormone (PTH), which is secreted only by the parathyroid gland, PTHrP, the protein encoded by PTHLH, is expressed and secreted by a few normal tissues and many tumor cells in an autocrine or paracrine way." (PMID 25539663, 2014).
tumor (continued). "Since the receptor for these ligands, EGFR, plays a critical role in cancer cell migration and tumor metastasis, we investigated whether EGFR signaling in the mesenchymal progenitors mediates the chemotactic effects of conditioned media from PTH-treated osteoblasts." (PMID 23300521, 2012). "Since inflammation did not influence tumor weight, the observed association could indicate a functional relationship between tumor-infiltrating CD8+ lymphocytes (which were the predominating cell type) and tumor PTH secretion." (PMID 28855268, 2017). "The study revealed clear between-country differences for parathyroid hormone (PTH), adiponectin, folate, and vitamin B12 (VB12), but none for other analytes including most of commonly tested tumor markers and reproductive hormones." (PMID 33411740, 2021). "The tumor cells did show some weak scattered staining for S100 but were negative for myogenin, desmin, smooth muscle actin (SMA), parathyroid hormone (PTH), thyroid transcription factor-1 (TTF-1), and thyroglobulin." (PMID 25610687, 2014). "Immunohistochemically, tumor cells were negative for thyroid transcription factor-1 (TTF-1), negative for thyroglobulin, negative for chromogranin A (positive for normal parathyroid tissue within the nodule), positive for PTH, and positive for parafibromin." (PMID 33978837, 2021).
endocrine disorder (198 papers, 2007 to 2026). "Non-parathyroid hormone-related causes include thiazides and lithium, malignancies involving bone metastases, endocrine disorders, and granulomatous diseases." (PMID 33718400, 2021). "PHPT is an endocrine disorder characterized by the autonomous, excessive secretion of parathyroid hormone (PTH), leading to a dysregulation of calcium homeostasis." (PMID 41473619, 2025). "Endocrine hormones like estrogens and parathyroid hormone influence bone metabolism and immune responses, which are important to OA, and endocrine disorders can exacerbate musculoskeletal issues, including OA." (PMID 41256619, 2025). "PHPT manifests as an endocrine disorder characterized by the overproduction and release of PTH from one or more of the four parathyroid glands." (PMID 38975429, 2024). "PHPT is a common endocrine disease characterized by elevated or inappropriate secretion of serum PTH level and increased serum calcium." (PMID 37415163, 2023). "Patients with HCM due to endocrinopathies had significative higher PTH median level (460 ng/mL, IQR, 197.5; 589 versus 8.5, IQR: 3.9; 16.25; P < 0.0001)." (PMID 31776814, 2019). "Undiagnosed metabolic or endocrine disorders of calcium, vitamin D, and parathyroid hormone (PTH) impair fracture healing, and are considered predisposing factors in up to 85% of nonunions." (PMID 26535187, 2015). "HPT is an endocrine disorder characterized by increased secretion of the parathyroid hormone (PTH)." (PMID 37614292, 2023). "HypoPT, instead, is a rare endocrine disorder caused by chronic deficiency or absence of PTH." (PMID 34746197, 2021). "Although endocrinopathies have been reported as major components of MAS, in both cases reported here, thyroid and parathyroid hormone levels were within normal ranges, while precocious puberty was present in the first case." (PMID 31395055, 2019). "Additionally, parathyroid hormone (PTH), when present at high levels–as in some endocrine disorders–directly stimulates osteoclast formation and accelerates bone resorption." (PMID 40761854, 2025). "Furthermore, this endocrine disorder may be a model for the assessment of CaCO3 per se, without the influence of PTH on the temporal variations of calcemia and phosphatemia." (PMID 29279189, 2019).
cancer (184 papers, 2003 to 2026). A tumor composed of atypical neoplastic, often pleomorphic cells that invade other tissues. "By combining receptor antagonism with bone-targeted delivery, these agents selectively disrupt the interaction between cancer cells and bone, mitigating osteolytic damage and thereby avoiding the risks associated with anabolic PTH agonists." (PMID 40941030, 2025). "In total, 98% of cancers are functioning tumours associated with more frequent bone and kidney disease, while only 2% are characterized by normal serum levels of PTH and calcium along with the evidence of a palpable and invasive mass." (PMID 38027123, 2023). "Néanmoins, certains auteurs considèrent qu'un taux de PTH inférieur à 4 fois la normale rend le diagnostic de cancer parathyroïdien très peu probable." (PMID 28819506, 2017). "The anabolic actions of PTH make it an attractive candidate for reducing fracture risk in post-irradiation cancer-induced bone disease." (PMID 27332712, 2016). "Although mGPS is usually used to predict outcome in cancer patients, our results indicate that serum PTH levels were strongly associated with increased mGPS." (PMID 24782595, 2014). "KEGG pathway enrichment analysis demonstrated that these overlapping genes were predominantly enriched in pathways such as the IL-17 signaling pathway, cancer-associated pathways, viral and bacterial infection-related pathways, and parathyroid hormone synthesis, secretion, and action." (PMID 41305834, 2025). "Hence, the aim of the present study was to investigate a possible association of PTH levels on cancer outcome in a large pediatric cohort." (PMID 39141058, 2024). "Very tightly linked to calcium regulation, PTH has also been linked to cancer development." (PMID 35662320, 2022). "Our study provides the cues from the Chinese sib-pair samples, implying that repression of PTH and cancer-related pathways might be associated with MDD in these people." (PMID 34667146, 2021). "Next, we assessed whether total serum calcium, ionized calcium, vitamin D, and PTH levels are associated with specific primary cancer types." (PMID 34357109, 2021). "Similarly, other compounds, such as the parathyroid hormone (PTH) and PTH-related protein (PTHrP) peptides, are currently being tested, while their limited applicability in association with cancer still needs to be clarified." (PMID 29089584, 2017). "However, PTH drugs can only be administrated by injection and for only 2 years due to the risk of cancer." (PMID 24465596, 2014). "High levels of calcium (> 14 mg/dl) and PTH (> 800 pg/ml or more than 10 times the upper normal value), associated with a single enlarged gland (> 3 cm) or signs of adjacent soft tissue invasion at sonography, should guide the clinician to search for carcinoma." (PMID 35872978, 2022). "However, in cancer patients, electrolyte imbalance may occur even in the absence of significant fluid abnormalities due to secondary causes (eg, altering parathyroid hormone [PTH] levels or drug side‐effects)." (PMID 34185420, 2021). "In cases with discordant imaging and multiple lesions, bilateral internal jugular venous parathyroid hormone sampling serves as a decisive adjunct to guide en bloc resection when carcinoma is suspected." (PMID 41985543, 2026). "In our study, carcinoma cases exhibited PTH values approximately tenfold above the normal range and were associated with more severe biochemical abnormalities, including higher serum calcium and lower phosphate levels." (PMID 41509026, 2026). "Mice exposed to the virosome containing PTH-rP have cytotoxic efficacy against class I-matched cancer cells that manufacture PTH-rP, as well as a multi-epitopic CTL-mediated immune response." (PMID 41157238, 2025). "Myeloid cell DEGs were enriched in 256 pathways, such as proteoglycans in cancer, parathyroid hormone synthesis, secretion and action, and phosphatidylinositol signaling system, indicating diverse regulatory and signaling functions." (PMID 41154754, 2025).